HGF (hepatocyte growth factor)
Diseases named in the same sentence as HGF in open-access papers (continued):
Sharing a sentence is not in itself a finding about the gene and the disease.
COVID-19 (continued). "Additionally, IL-2Rα, IL-5, IL-10, HGF, and IP-10 were correlated with SOFA scores in patients with severe-to-mild COVID-19 at different disease stages." (PMID 38710800, 2024). "Cytokines/chemokines (IL-6, CXCL-10 (IP-10), HGF, MIG, MCP-1, and G-CSF) and lipid mediators (TxB2, 11-HETE, 9-HODE, 13-HODE, 5-HETE, 12-HETE, 15-HETE, 14S-HDHA, 17S-HDHA, and 5-oxo ETE) were significantly elevated in COVID-19 patients compared to controls." (PMID 37685858, 2023). "HGF often neutralizes transforming growth factor beta-1 (TGFB1), another cytokine involved in apoptosis, which is expressed at high levels in patients with COVID-19 and has been suggested to affect the patient by immunopathological devices." (PMID 36851766, 2023). "Our data also identified CRP, among all investigated analytes, to best discriminate between severe and non-severe forms of disease, while LDH, sTREM-1 and HGF proved to be excellent mortality predictors in COVID-19 patients." (PMID 37388734, 2023). "Among these proteins, KRT19, TOP2B, AREG, HGF, CKAP4, ITGB6, and NCF2 had a higher expression (> twofold) in plasma samples of severe compared to moderate COVID-19 patients, whereas CLEC4C and LTA were among the few proteins that were expressed at lower levels in severe patients." (PMID 36829233, 2023). "On the contrary, IL-6 (p=0.034), M-CSF (p=0.001) and IP-10 (p=0.023) levels were significantly up-regulated in COVID-19 patients compared with the negative subjects whereas HGF and CTAK demonstrated a tendency to be significantly higher." (PMID 36148234, 2022). "pGSN alone outperformed cytokines (IL-6, IP-10, HGF and M-CSF) in discriminating COVID-19+ patients from non-COVID-19 suggesting that pGSN is a potential biomarker indicative of COVID-19 infection." (PMID 36148234, 2022). "Therefore, the early detection of HGF, IL-1α, and IL27 plasma levels in patients in COVID-19 patients can provide useful information for getting quickly intensive treatment as well as providing possible therapeutic targets." (PMID 34066892, 2021). "Up-regulation of HGF reflects the most powerful counter-regulatory mechanism of the host immune response to antagonize the pro-inflammatory cytokines including CXCL13 and to prevent lung fibrosis in COVID-19 patients." (PMID 34373466, 2021). "In this regard, we hereby report that HGF, IL1α, and IL27 contribute to the deterioration of the disease and the adverse outcome of COVID-19 revealing these three compounds as novel biomarkers but as future therapeutic targets in COVID-19." (PMID 34066892, 2021). "Also of interest is that sustained upregulations of HGF, TNFSF14 and CASP-8 have been observed in studies on COVID-19 patients as an indicator for severe disease." (PMID 34948231, 2021). "Liability to any COVID-19 was nominally associated with several cytokines, such as granulocyte colony-stimulating factor (GCSF) and hepatocyte growth factor (HGF) but not after correction." (PMID 34163532, 2021). "First, we identified six cytokines and chemokines, including HGF (significant difference in cohort 1 and cohort 4) and IL-10, IP-10, SCGF-β, IL-16, and IL-18 (significant difference in cohort 3 and cohort 4), that consistently showed variations in COVID-19 in different cohorts." (PMID 38710800, 2024). "Only nine of these cytokines were shared between the two profiles Furthermore, the salivary hepatocyte growth factor (HGF) and fibroblast growth factor 2 were statistically significantly lower in COVID-19-positive patients compared to the controls (<0.05) but not in blood." (PMID 38617584, 2024). "In addition, HGF and MCP-1 distinguished moderate from severe COVID-19." (PMID 35421120, 2022). "After adjustment for age, BMI, CCI score, and multiple testing, men with severe COVID-19 had higher median (IQR) concentrations of serum IL-6 (61 pg/mL vs 26 pg/mL; P = .003) and hepatocyte growth factor (HGF; 994 [383-2308] pg/mL vs 330 pg/mL; P = .002) compared with men without severe COVID-19." (PMID 34032853, 2021).
COVID-19 (continued). "Thus, HGF and CXCL13 were the best predictors of COVID-19 severity and ICU admission." (PMID 34373466, 2021). "The concentrations of CTACK, GRO-α, IP-10, MIG, basic-FGF, HGF, PDGF- BB, GM-CSF, SCF, LIF, and TRAIL were higher in asymptomatic/mildly symptomatic COVID-19 patients (stage 1) and COVID-19 patients with pneumonia without respiratory failure (stage 2)." (PMID 38239363, 2023). "In the present study, all COVID-19 patients exhibited significantly higher levels of IL-6, CXCL-10, HGF, MIG, MCP-1, and G-CSF than the non-COVID-19 respiratory disease controls." (PMID 37685858, 2023). "The levels of pGSN/IP-10, pGSN/CTAK, pGSN/IL-6 and pGSN/M-CSF (but not pGSN/HGF) were elevated in patients that were discharged, suggesting that pGSN levels in combination with inflammatory cytokines especially pGSN/IL-6, may predict mild and favorable outcomes for hospitalized COVID-19 patients." (PMID 36148234, 2022). "The mean levels of pGSN/IL-6, pGSN/M-CSF, pGSN/HGF, pGSN/IP-10 and pGSN/CTAK were determined and compared between COVID-19 patients and COVID-19 negative controls." (PMID 36148234, 2022). "HGF is a growth factor secreted by alveolar fibroblasts shown to be elevated in bronchoalveolar lavage fluid of patients with ARDS and in plasma of patients with acute COVID-19 illness; however, the plasma levels after COVID-19 recovery have not been previously reported." (PMID 34111030, 2021).
ovarian carcinoma (91 papers, 2000 to 2026). A malignant neoplasm originating from the surface ovarian epithelium. "When exposed to neutralizing antibodies for TGF-ß and HGF, the loss of each of the junctional proteins was inhibited in senescent mesothelial cells as well as the trans-mesothelial invasion of ovarian cancer cells." (PMID 35574025, 2022). "Serum HGF (sHGF) was determined by enzyme‐linked immunosorbent assay in a total of 471 serum samples from 82 healthy controls and 113 patients with ovarian cancer (88.5% with ≥ FIGO III)." (PMID 33738970, 2021). "The HGF/cMET pathway mediates invasion and migration of ovarian cancer cells, and upregulation of HGF/cMET pathway components has been associated with poor prognosis." (PMID 33738970, 2021). "HGF is associated with an induction of mitochondrial oxidative stress, which in return contributes to HGF-dependent pro-senescence activity of ovarian cancer cells." (PMID 33050319, 2020). "Among the growth factors accumulated in ascites, HGF has recently been implicated in the implantation of endometrial cells and ovarian cancer cells in the peritoneum via a MMT." (PMID 26426054, 2015). "TSP-1 immunoreactivity was negatively associated with HGF immunoreactivity in human ovarian cancer tissues." (PMID 23749112, 2013). "If the underlying mechanism of HGF/c-Met axis in ovarian cancer could be better understood, the new improving therapeutic agents will be developed in the future." (PMID 28258248, 2017). "In addition, in a recent study, HGF was used as a blood-based independent predictive biomarker in patients with ovarian cancer, implying that it might be used as a primary diagnostic marker." (PMID 35630066, 2022). "However, as with other cancer types, multiple prior investigations have shown that cancer growth is linked to an abnormally active HGF/c-MET axis in subsets of all four major histocytes in ovarian cancer (high-grade serous, clear cell, mucinous, and endometroid)." (PMID 35630066, 2022). "In ovarian cancer, HGF activates a specific c-Met/PI3K/Akt signaling axis through a positive feedback loop that promotes cancer stemness and contributes to drug resistance." (PMID 41373619, 2025). "In ovarian cancer, factors including HGF, VEGFA, IGF, and stromal-derived BMPs drive CSC plasticity and contribute to relapse after platinum therapy." (PMID 41373619, 2025). "Peritoneal fluid in ovarian cancer contains increased concentrations of HGF (hepatocyte growth factor), TGF-β1 (transforming growth factor beta-1), and GRO-1 (growth-related oncogene-1)." (PMID 38791014, 2024). "For the remaining agents, HGF promotes the proliferation of ovarian cancer cells by up-regulating c-Met/PI3K/Akt and GRP78 signaling." (PMID 39595551, 2024). "Along the same line, neutralizing antibodies against HGF inhibited the migration of SKOV3 ovarian cancer cell line." (PMID 35565396, 2022). "Many studies have been conducted to treat ovarian cancer using small molecules and antibody drugs, which are new candidates targeting HGF/c-MET." (PMID 35630066, 2022). "Transfection of CaOV3 and SKOV3 ovarian cancer cells with HGF prompted a change to a fibroblastic-like shape and activation of p70 S6 kinase." (PMID 35565396, 2022). "Although ovarian cancer cells exhibit high expression of c-Met, they are reliant on the ascitic microenvironment for HGF." (PMID 35676254, 2022). "Previous research has shown that HGF is detectable in primary ovarian cancer tissue and that the amount increases with tumor stages." (PMID 35630066, 2022). "CAFs-derived hepatocyte growth factor (HGF) or human recombinant HGF can promote cell proliferation in the ovarian cancer cell lines SKOV3 and HO-8910 by activating the c-Met/PI3K/Akt and GRP78 signaling pathways." (PMID 35681617, 2022). "The ascitic microenvironment contains high levels of HGF, which promotes metastasis and invasiveness of ovarian cancer through activation of c-Met." (PMID 35676254, 2022).
ovarian carcinoma (continued). "Several studies found that CAF-derived HGF increased chemoresistance in ovarian cancer cells in vitro and in vivo via upregulating MET/PI3K/Akt signaling." (PMID 35630066, 2022). "HGF and its receptor c-Met are involved in malignant transformation, and c-Met overexpression in ovarian cancer is a prognostic factor." (PMID 35676254, 2022). "In this review, we discuss the role of the HGF/c-MET axis in ovarian cancer metastasis and prognosis, as well as other cancer types." (PMID 35630066, 2022). "We observed that under conditions of shear stress or HGF treatment, where miR-199a-3p is downregulated, ovarian cancer cells were able to form more spheroids under stem cell-selective conditions, indicating an association between miR-199a-3p and stemness." (PMID 35676254, 2022). "HGF is a growth factor released by CAFs that stimulates ovarian cancer cell proliferation, migration, and invasion." (PMID 35574025, 2022). "Addition of HGF, which triggered c-Met phosphorylation, was able to overcome the inhibition of ovarian cancer cell invasion by α5β1 blocking antibody or siRNA, demonstrating that integrin acts upstream of c-Met in an HGF-independent manner." (PMID 36330337, 2022). "These included, among others, VEGF—known to promote ovarian cancer neovascularization, TGF-β1—recognized as a mediator of EMT and increased ovarian cancer cell invasion, proinflammatory and ovarian cancer cell growth-promoting IL-6, and pro-migratory HGF." (PMID 35883110, 2022). "As a result, multiple studies have verified the synergistic reduction of tumor development in ovarian cancer cells in vitro and in vivo when chemo drugs are combined with HGF or c-MET targeting." (PMID 35630066, 2022). "There is also evidence from in vitro studies that HGF signaling contributes to matrix metalloproteinase 9‐mediated invasion and migration of ovarian cancer cells." (PMID 33738970, 2021). "In ovarian cancer, the HGF/cMET pathway is aberrantly activated and contributes to matrix metalloprotease 9 (MMP9)‐mediated invasion and malignant progression." (PMID 33690968, 2021). "This study investigated the clinical relevance of circulating HGF in serum of patients with ovarian cancer." (PMID 33738970, 2021). "It was reported that HGF is detectable in primary ovarian cancer tissue and its level is increased in higher tumor stages." (PMID 33738970, 2021). "It has been found that hepatocyte growth factor (HGF) in the tumor microenvironment can lead to chemotherapy resistance in ovarian cancer by up-regulating expression of the PI3K/Akt signaling pathway." (PMID 33083827, 2020). "Particularly intriguing activity was recently observed in ovarian cancer cell-derived HGF, which appeared capable of inducing accelerated senescence in HPMCs, actively contributing to the formation of a metastatic niche by these cells within the peritoneum." (PMID 32012719, 2020). "CAF-derived HGF also activates the proliferation of ovarian cancer cells thorough c-Met/PI3K/Akt signaling." (PMID 33050576, 2020). "The levels of HGF secreted by the A2780/luc, OVCAR-3, SKOV3, Caov-3, and JHOC-5 ovarian cancer cells into the culture media measured using enzyme-linked immunosorbent assay (ELISA) were 794,246.0, 90.5, 415.4, 1,140.4, and 368.1 pg/mL, respectively." (PMID 31355133, 2019). "HGF is expressed in normal ovarian epithelial cells and benign ovarian tumor cells, but to a higher degree in ovarian cancer cells." (PMID 31355133, 2019). "This study assessed the effects of YYB-101, a humanized monoclonal anti-HGF antibody, on the growth and metastasis of ovarian cancer cells." (PMID 31355133, 2019). "Our results demonstrated that high levels of HGF were secreted by various ovarian cancer cell lines and HGF was involved in the increased migration and invasiveness of ovarian cancer cells." (PMID 31355133, 2019). "The results of the present study suggest that HGF has promise as a target molecule for the treatment of patients with ovarian cancer." (PMID 31355133, 2019).
ovarian carcinoma (continued). "HGF also stimulates the proliferation and inhibits the apoptosis of ovarian cancer cells, thereby enhancing cell survival." (PMID 31355133, 2019). "In the present study, we firstly isolated CAFs from tumour tissues of the patients with ovarian cancer and demonstrated that the hepatocyte growth factor (HGF) was highly expressed in the supernatants of CAFs." (PMID 28258248, 2017). "107_A07 Fab dose-dependently inhibited HGF/SF-induced cell migration of SKOV-3 human ovarian cancer cells and U87MG human glioblastoma cells." (PMID 28827556, 2017). "c-Met, as a specific receptor of HGF, is highly expressed in a number of tumour types including ovarian cancer." (PMID 28258248, 2017). "HGF expression was shown to be clearly increased in urogenital cancers such as urinary bladder, prostate and ovarian cancer." (PMID 28212658, 2017). "Taken together, these data indicated that HGF in the CAF matrix induced hyposensitivity to PAC in ovarian cancer cells and the effect of HGF was mediated through c-Met." (PMID 28258248, 2017). "In short, HGF/c-Met attracts more and more attention as a potential therapeutic target in ovarian cancer." (PMID 28258248, 2017). "In the course of stroma–cancer cell interactions, human ovarian fibroblasts and MSC produced and secreted HGF, leading to elevated growth and migration of ovarian cancer cells coinciding with c-Met phosphorylation at Tyr1349." (PMID 28212658, 2017). "In vitro, HGF mediated an epithelial-to-mesenchymal transition and sustained anchorage-independent growth of ovarian cancer cells." (PMID 26648788, 2015). "The final aspect of ovarian cancer metastasis addressed here is the ability of INC280 to inhibit HGF-induced adhesion to peritoneum, one of the most important, and defining, features of ovarian cancer." (PMID 26138303, 2015). "Elevated serum levels of HGF were exhibited in >90 % of tumors and correlated to shorter overall survival of ovarian cancer patients." (PMID 26648788, 2015). "All growth factors were examined at a dose of 10 ng/mL, reflecting the concentrations reported for HB-EGF and HGF in ascites fluid of ovarian cancer patients." (PMID 26648788, 2015). "Regarding this idea, in vitro experiments have shown that ovarian cancer ascites enhances the migration and invasion of both patient-derived peritoneal MCs and ovarian cancer cells through HGF-dependent mechanisms." (PMID 26426054, 2015). "A cellular model (SCCOHT-1) of the aggressive small cell hypercalcemic ovarian carcinoma demonstrated constitutive chemokine and growth factor production including HGF." (PMID 26436697, 2015). "A number of c-MET inhibitors and HGF antagonists are currently under investigation, in both pre-clinical models of ovarian cancer, and clinical trials for multiple cancer types (reviewed in6 and19)." (PMID 26138303, 2015). "p70S6K activation can result from the enhanced expression and activity of cytokines and growth factors, such as hepatocyte growth factor (HGF) that characterizes ovarian cancer." (PMID 25193855, 2014). "Of note, hepatocyte growth factor (HGF) and its receptor c-MET were enhanced in those with aggressive ovarian cancer and were associated with refractory disease." (PMID 27382614, 2014). "Due to the direct involvement of HGF/c-Met in ovarian cancer aggressiveness, we believe that our data support the rationale for clinical trials of inhibitors of the HGF/c-Met axis in the context of the NACT setting." (PMID 24952592, 2014). "In these studies, HGF was used to activate p70S6K, because HGF is highly expressed in ascitic fluid of ovarian cancer patients, marking it as a major contributor to malignant spreading." (PMID 25193855, 2014). "Hepatocyte growth factor (HGF) can affect cell biological behavior though downregulation of TSP-1 in ovarian cancer and thyroid cancer." (PMID 23749112, 2013).